ULK2 (unc-51 like autophagy activating kinase 2)
Diseases named in the same sentence as ULK2 in open-access papers (continued):
Sharing a sentence is not in itself a finding about the gene and the disease.
ovarian carcinoma (continued). "Our experiments showed significant downregulation of ULK2 in ovarian cancer tissues." (PMID 38952983, 2024). "Our research has contributed significant insights into the role of ULK2 in ovarian cancer." (PMID 38952983, 2024). "Consequently, we deduced that ULK2 expression was significantly diminished in tissues of epithelial ovarian cancer." (PMID 38952983, 2024). "Therefore, the collective results suggest that ULK2 participates in tumor inhibition and could potentially be utilized as a novel prognostic biomarker for ovarian cancer." (PMID 38952983, 2024). "However, the function of ULK2 in ovarian cancer remains poorly understood at present." (PMID 38952983, 2024). "Samples of 59 diverse ovarian cancer cell lines from the HPA database were examined for expression levels of ULK2, which revealed low or no expression in numerous cell lines." (PMID 38952983, 2024). "Analysis of the GEPIA database revealed downregulation of ULK2 in various tumor tissues, including ovarian cancer, relative to the corresponding non-tumor counterparts." (PMID 38952983, 2024).
Sensory neuropathy (1 paper, 2019). Peripheral neuropathy affecting the sensory nerves. "This is the first demonstration that sensory neuropathy affects cardiac miRNA expression network targeting IGF-1, SLC2a-12, EIF-4e, and ULK-2, which may contribute to cardiac diastolic dysfunction induced by sensory neuropathy." (PMID 30823517, 2019). "This is the first demonstration that sensory neuropathy induced by capsaicin desensitization affects cardiac miRNA expression network targeting IGF-1, SLC2a-12, EIF-4e, and ULK-2, which may contribute to cardiac diastolic dysfunction induced by sensory neuropathy." (PMID 30823517, 2019).
Sepsis (1 paper, 2025). Sepsis is defined as life-threatening organ dysfunction caused by a dysregulated host response to infection. "The top five gene variables (MTF1, UBE2D2, DLAT, DLD, and ULK2) were selected as disease signature genes in the GLM model to construct a nomogram for predicting the incidence of sepsis-associated ALI." (PMID 38779731, 2025). "The expression of SLC31A1, CD274, ATOX1, MTF1, UBE2D1, DLD, and VEGFA was found to be upregulated, while that of DLST, UBE2D2, COX11, DLAT, GLS, FDX1, and ULK2 were significantly downregulated in patients with sepsis-associated ALI." (PMID 38779731, 2025).
tumor (13 papers, 2015 to 2025). "PTEN correlated with ULK2 in LGG indicated its tumor suppressive role and its deficiency has been associated with promoting tumors indirectly through the dysregulation of PI3K/AKT." (PMID 39348350, 2024). "However, our findings also revealed that overexpression of ULK2 influenced multiple signaling pathways linked to tumor progression, including fatty acid biosynthesis, fatty acid elongation and spliceosome, as identified through KEGG pathway analysis." (PMID 38952983, 2024). "Furthermore, a mounting number of studies suggest that ULK2 is implicated in cancer progression and therapy by influencing diverse cellular processes independent of its involvement in autophagy, rendering it a putative tumor suppressor gene." (PMID 38952983, 2024). "In vitro functional studies further demonstrated that overexpression of ULK2 significantly suppressed tumor cell proliferation, migration, and invasion." (PMID 38952983, 2024). "Nevertheless, a growing body of research indicates that ULK2 is downregulated in various tumor types, exerting inhibitory effects on tumor initiation and progression." (PMID 38952983, 2024). "Among the 22 CIBERSORT cell types, plasma cell and macrophage had significant differences (P <0.01/22) in abundance when comparing ULK2 between normal and tumor tissues from TCGA dataset." (PMID 36387235, 2022). "The tumor immune microenvironment plays a key role in disease development, therefore, we also analyzed the expression of ULK2 in different tumor immune cell types." (PMID 36387235, 2022). "Inactivation/loss of PKCλ/ι was found to induce ULK2 activity, which directly activates the TBK1-STING-IRF3 pathway, leading to IFN production and anti-tumor responses." (PMID 35365653, 2022). "The function of DAPK1 and ULK2 reported previously are consistent with the results of our study, which suggest tumor-suppressive roles in NB." (PMID 36530992, 2022). "WB analyses of snap-frozen tumor tissues from 6 clinical PDAC patients who had undergone radical resection showed that ULK2 protein expression was positively correlated with the levels of YAP (P = 0.0271) and PKM2 (P = 0.0044)." (PMID 34345207, 2021). "The findings suggest that ULK2 expression could therefore serve as a potential indicator for assessing tumor prognosis and as a focus for cancer treatment." (PMID 38952983, 2024). "CHI treatments stimulated BC cell apoptosis by promoting ULK2-mediated autophagy and increasing MCF-7 cell sensitivity to DOX, resulting in decreased tumor growth." (PMID 37069549, 2023). "Aside from affecting tumor angiogenesis, copper regulates autophagy through ULK1 and ULK2, as well as promoting tumor formation, growth, and metastasis." (PMID 36874011, 2023). "The results showed that the ULK2 and GABARAPL1 mRNA in the tumor tissues were significantly downregulated compared with those in the paracancerous tissues (p<0.05)." (PMID 34041016, 2021). "To evaluate the fundamental role of ULK1/2 on PKM2 expression in vivo, we examined PKM2 expression using immunohistochemistry (IHC) in subcutaneous tumor xenografts arised from nude mice that were inoculated with S-1 cells bearing ULK1, ULK2 or ULK1/2 shRNA." (PMID 34345207, 2021). "To confirm the reliability of the identified gene signature, we examined the ULK2 and GABARAPL1 expression levels by qRT-PCR, WB, and IHC using 8 pairs of OC tumor tissues and paracancerous tissues." (PMID 34041016, 2021). "However, when the concentration of copper at the tumor site is abnormal, copper can regulate autophagy through ULK1 and ULK2, and control protein quality through UBE2D2, which in turn affects the growth and progression of the tumor." (PMID 36891559, 2023). "The pivotal function of IGFBP3 in the insulin signaling axis may account for its regulatory role, representing a novel contributory mechanism to the tumor suppressor effect of ULK2 that is independent of its involvement in autophagy control." (PMID 38952983, 2024).
cancer (12 papers, 2020 to 2025). A tumor composed of atypical neoplastic, often pleomorphic cells that invade other tissues. "ATG5, GABARAP, ATG7, and ULK2 had a higher frequency of loss mutations in the pan-cancer analysis." (PMID 34636718, 2021). "The ability of Cu to facilitate cellular respiration through COX function and promotion of autophagy through ULK1 and ULK2 activation enhances cancer cell survival." (PMID 36430490, 2022). "In our findings, ULK2 was not only differentially expressed on cancer cell but also macrophage and plasma cell." (PMID 36387235, 2022). "The activation of ULK1 and ULK2 by Cu enhances energy production in cancer cells, which sustains the energetic cost of continuous cell growth and division." (PMID 36430490, 2022). "In a pan-cancer analysis, different changes in the ULK2 transcript were observed depending on the cancer types." (PMID 36387235, 2022). "As reported by others, the inhibition of autophagy by promoter methylation of ULK2, which leads to downregulation of transcript levels, was essential for cancer growth under the genetic background of ATG5." (PMID 34901004, 2021). "Importantly, several key ferroptosis drivers and suppressors, including MAPK1, TLR4, ATM, ULK2, NFS1, and HMOX1, have been identified, offering potential therapeutic targets to modulate cancer cell susceptibility to ferroptosis." (PMID 40868287, 2025). "Given the evidence supporting Myc as a regulator of cancer stemness, and our findings that ULK2 may promote the CSL feature of chemoresistance in SORE6+ cells, we asked if the expression level of ULK2 is regulated by Myc." (PMID 38203816, 2024). "In other cancer types, ULK2 could compensate for ULK1 downregulation and, in the majority of the cases, no marked changes in expression have been found." (PMID 32913252, 2020). "However, there are contradictory results about the role of ULK2 in cancers." (PMID 36387235, 2022). "Among these, open reading frames of at least 23 genes (23/42 = 55%), including cancer genes such as ERBB2, FOLH1 and ULK2, were predicted to be altered by these SMNTs and their combined structural variant events in the vicinity." (PMID 32024997, 2020). "ULK2 appears to be a key player in enhancing autophagy-mediated chemoresistance in SORE6+ cells and may contribute to cancer stemness and relapse." (PMID 38203816, 2024). "For example, there is no clear evidence of the contributions of ULK2 to STS progression, thus the role for this protein in STS patients remains unknown, as limited information in general is available for this cancer type." (PMID 36430490, 2022).
infection (5 papers, 2020 to 2024). The state of being infected such as from the introduction of a foreign agent such as serum, vaccine, antigenic substance or organism. "We used HRM qRT-PCR to confirm the presence of mutated Ulk1 and Ulk2 RNAs transcripts after the infection with the gRNAs." (PMID 32985978, 2020). "Many genes in the autophagy and mitophagy signaling pathways, such as ULK2, BNIP3, WIPI1 and CTSB, presented significantly upregulated expression profiles following infection." (PMID 39650642, 2024). "On the other hand, in the NH4Cl group, the relative expression of MAP1LC3A, ULK2, and SQSTM1 was higher at early (6 to 14 hpe) and late time points (18 to 30 hpe) of the experimental infection in comparison with the artificial seawater group (p ≤ 0.05)." (PMID 35444958, 2022). "The results revealed that the relative expression of ULK2, SQSTM1, and MAP1LC3A was significantly higher in the virus group in comparison with the artificial seawater group at later time points of the experimental infection (18 to 30 hpi; p ≤ 0.05)." (PMID 35444958, 2022).
metabolic disorders (1 paper, 2024). "Therefore, our findings revealed that high alkalinity leads to metabolic disorders, induces oxidative stress and triggers mitochondrial autophagy through the miR-140-5p–ULK2 axis." (PMID 39040116, 2024).
myopathy (1 paper, 2019). A disease of the muscle in which the muscle fibers do not function properly. "In fact, adult ULK2 deficiency in muscle causes accumulation of insoluble ubiquitinated protein aggregates and a myopathy characterized by myofiber weakness, atrophy, and degeneration." (PMID 31361156, 2019).
ULK2 also shares sentences with these, for which no sentence is quoted: Alzheimer disease (3 papers); schizophrenia (3); lung carcinoma (2); acute myeloid leukemia (1); adenomyosis (1); Anxiety (1); astrocytoma (1); brain arteriovenous malformation (1); cerebral infarct (1); cognitive decline (1); colorectal cancer (1); congenital heart disease (1); corneal dystrophy (1); Crohn disease (1); hyper-IgE syndrome (1); IgA Nephropathy (1); Immunodeficiency (1); ischemia (1); laryngeal carcinoma (1); leukemia (1); lung adenocarcinoma (1); metastatic disease (1); neurodevelopmental disorder (1); neuropathy (1); Parkinsonism (1); protein folding disorders (1); rheumatoid arthritis (1); vascular dementia (1).